MITF (melanocyte inducing transcription factor)
Diseases named in the same sentence as MITF in open-access papers (continued):
Sharing a sentence is not in itself a finding about the gene and the disease.
cutaneous melanoma (50 papers, 2008 to 2026). A primary melanoma arising from atypical melanocytes in the skin. "Miskolczi and colleagues found that the presence of fibroblast tumor growth factor-β suppressed YAP/PAX3-mediated MITF expression and was associated with a dedifferentiated phenotype in cutaneous melanoma." (PMID 39804140, 2025). "Similar to the situation in cutaneous melanoma, we propose that MITF loss in UM is related to de-differentiation to a less favourable EMT profile and inflammation." (PMID 37240204, 2023). "MITF is a master regulator of melanocyte development, function, and pigmentation and, in cutaneous melanoma, has been linked to a proliferative, non-invasive phenotype." (PMID 37240204, 2023). "Variants in genes of low to moderate penetrance related to skin pigmentation and differentiation of melanocytes, such as the MC1R and MITF genes, are also of great importance in determining the risk for cutaneous melanoma." (PMID 37895483, 2023). "In cutaneous melanoma, MITF loss has been linked to an increased expression of stem cell markers, a shift in epithelial-to-mesenchymal transition (EMT)-related factors, and increased inflammation." (PMID 37240204, 2023). "Several papers on cutaneous melanoma have reported MITF silencing to be associated with an inflammatory secretory phenotype." (PMID 37240204, 2023). "Supporting this model, positive MITF staining in the primary tumour was associated with a better survival and lower rates of lymph node involvement in cutaneous melanoma patients." (PMID 35682684, 2022). "MITF locus is amplified in 7.9% of skin melanomas, while in our dataset, MITF somatic mutations are quite rare, with a frequency of 1.7%." (PMID 32850962, 2020). "BRAFV600E, the most frequent mutation in cutaneous melanomas, downregulates the expression of MITF and its downstream effectors operating in the differentiation pathway, while MITF expression is increased by BRAF inhibitors." (PMID 33276788, 2020). "Taken together, we surmise that MITF causes cellular proliferation and oncogenesis in most posterior uveal melanomas and some cutaneous melanomas with MITF amplification." (PMID 22848417, 2012). "Here, we review the molecular networks associated with MITF in skin melanoma development and progression." (PMID 22046555, 2011). "Moreover, the modulation of MITF expression in cutaneous melanoma cells has been shown to cause changes in the inflammatory response." (PMID 37240204, 2023). "MITF has also been associated with the process of EMT in cutaneous melanoma." (PMID 37240204, 2023). "However, low MITF expression in cutaneous melanoma cells has also been linked to phenotype switching and drug resistance." (PMID 35682684, 2022). "Indeed, MITF expression was significantly associated with poor outcome in skin cutaneous melanoma (SKCM) (p < 0.05, log-rank test)." (PMID 33293474, 2020). "However, as in cutaneous melanoma, MITF inhibition might be associated with a stem cell-like phenotype." (PMID 35682684, 2022).
cutaneous melanoma (continued). "In cutaneous melanomas, MiTF expression was correlated with a greater number of tumors, whereas p38 expression was associated with smaller tumors, the presence of a lymphocytic infiltrate, and prolonged survival." (PMID 41604042, 2026). "The transcriptional co-activator YAP, known to translocate into the nucleus in response to ECM stiffening in various cell types, promotes MITF expression in uveal and cutaneous melanoma cells and serves as MITF cofactor in uveal melanoma." (PMID 40973828, 2025). "The MITF also positively regulates the expression of Bcl2, an anti-apoptotic factor, in normal melanocytes and human cutaneous melanoma cells." (PMID 39000342, 2024). "It has been reported that MITF is frequently expressed in the BRAF-mutant subtype of cutaneous melanoma, as determined by TCGA data analysis." (PMID 38351314, 2024). "MITF-low cutaneous melanoma cells display a higher expression of stem cell markers (OCT4 and NANOG) and are able to produce larger tumours when injected into nude mice." (PMID 35682684, 2022). "In contrast, ATF4 (activating transcription factor 4), and JUN, which both integrate stress signals, repress MITF expression and trigger cutaneous melanoma cell dedifferentiation." (PMID 35682684, 2022). "MITF plays a dual role in cutaneous melanoma, based on its expression levels and activity; however, there is controversy surrounding this matter." (PMID 35159049, 2022). "Only a few studies analysed the presence and function of MITF in UM and, as for cutaneous melanoma, its role seems to be complex: some studies classify MITF as pro-oncogenic, and others mention its expression as a feature of low-risk tumours." (PMID 35682684, 2022). "Cutaneous melanoma cells exposed to hypoxia have a higher HIF1α expression and lower MITF expression and give rise to larger tumours and more frequent metastases." (PMID 35682684, 2022). "Other mutations and genetic alterations are known to be present in cutaneous melanoma, such as CDKN2A mutation, PTEN loss, and amplification of MITF, EGFR, CCDN1, cMET, and cKIT." (PMID 35682684, 2022). "In line with that, MITF has been reported as a critical downstream target of the HAT (histone acetyl transferase) p300 promoting human cutaneous melanoma growth." (PMID 35682684, 2022). "On the other hand, MITF has been reported to exert an antiproliferative effect in cutaneous melanoma cells, essentially via p21 regulation." (PMID 35682684, 2022). "To simplify this task, we have identified a small set of genes based on the master regulators of cutaneous melanoma transcriptional states, i.e., TEADs and MITF." (PMID 36271142, 2022). "We reviewed the literature regarding the role and regulation of MITF expression and its function in normal cutaneous melanocytes and compared its expression and function between cutaneous melanoma and UM cells." (PMID 35682684, 2022). "TGFβ antagonizes MITF function, represses pigmentation and stimulates the motile ability of cutaneous melanoma cells." (PMID 35682684, 2022). "We review the literature about the role of MITF in normal melanocytes, in cutaneous melanoma, and in UM." (PMID 35682684, 2022). "Cutaneous melanoma cells switch between MITF-high and MITF-low states in different phases of tumour development." (PMID 35682684, 2022). "Many of them were previously appreciated in the genome of skin melanomas (e.g., MITF, NOTCH2, PD-L1 and JAK2 amplifications, or CDKN2A deletions); however, the CNAs in genomic locations harboring PAX5, ETS1, BCL7, RAD51, APAF1, FOXO3 and CTNNA1 are novel." (PMID 33779796, 2021). "Among the analyzed phenotypic features, we included dermoscopic findings of histopathologically diagnosed dysplastic nevi (DN) and cutaneous melanomas in MITF+ and MITF−." (PMID 32054529, 2020). "Our findings in this study support the different biological effects of MITF on cutaneous melanomas and posterior uveal melanomas." (PMID 22848417, 2012).
cutaneous melanoma (continued). "Expression patterns, functions, and many target genes of MITF have been reported by a number of groups, though the complicated functions of MITF in skin melanoma development and progression are still not well understood." (PMID 22046555, 2011). "Tumoral cells in cutaneous melanoma as well as in metastases were also labelled with the MITF antibody." (PMID 18442364, 2008). "In cutaneous melanoma, evidence points towards an inverse correlation between MITF and inflammation: MITF knockdown has shown a correlation with an increased inflammatory phenotype in cutaneous melanoma cell lines, with an inhibitory effect of MITF on the inflammatory response." (PMID 37240204, 2023). "Moreover, the critical melanocyte transcription factor MITF is essential for the development and maintenance of cutaneous melanomas but acts as a tumor suppressor in uveal melanoma." (PMID 37577930, 2023). "The role of MITF has been extensively studied in cutaneous melanoma." (PMID 35159049, 2022). "However, inhibitors of HDAC (histone deacetylase) have also been shown to decrease MITF expression and to inhibit tumour growth in a human cutaneous melanoma xenograft model." (PMID 35682684, 2022). "MITF has been extensively studied in skin melanocytes and cutaneous melanoma over the past decades." (PMID 35682684, 2022). "Consequently, MITF knockdown in human cutaneous melanoma cell lines promotes a growth arrest through induction of a senescence-like phenotype." (PMID 35682684, 2022). "The analysis of the phenotypic traits of patients with MITF germinal mutations has revealed an association of this mutation with high mole count, onset of skin melanoma before the age of 40 and non-blue eye color." (PMID 34442055, 2021). "Moreover, immunohistochemical analyses of a large panel of primary human cutaneous melanomas (n = 136) spotted onto tissue microarrays (TMA) revealed a moderate but significant correlation between MITF and GTF2H1 at the protein level." (PMID 30651597, 2019). "In cutaneous melanoma, nests of MITF+ cells expressed RACK1 protein." (PMID 18442364, 2008). "Like cutaneous melanoma, MITF inhibition may activate the NFkB pathway." (PMID 35682684, 2022). "Loss of pigmentation in metastases compared to primary tumors is commonly observed in cutaneous melanoma, and although not completely understood, it can be brought about by different mechanisms, such as premature degradation of melanogenic proteins or downregulation of MITF transcription program." (PMID 21494657, 2011). "Three cutaneous melanoma cell lines (C013M, MeWo and NM177) were classified as transitory, as they expressed elevated levels of MITF and Melan A, and intermediate/high levels of AXL and/or NGFR." (PMID 34073253, 2021). "Recently, studies of aberrant miR-182 expression demonstrated that miR-182 promotes cutaneous melanoma metastasis by suppressing the transcription factors FOXO3 and MITF." (PMID 22848417, 2012). "Investigating 448 cutaneous melanomas from the TCGA PanCancer Atlas, we discovered a positive correlation between high ATP1A1 mRNA expression and markers of differentiation and pigmentation (MITF, SOX10, TYR, MLANA)." (PMID 38178183, 2024). "As control, we interrogated Skin Cutaneous Melanoma (SKCM) data to evaluate the correlation data of MITF not only with ZFR, but also with its well-known target gene, namely Tyrosinase (TYR)." (PMID 38472212, 2024). "Although it has been studied extensively in cutaneous melanoma, the role of MITF in uveal melanoma (UM) has not been explored in much detail." (PMID 35682684, 2022). "Moreover, the tumor diversity with pigmentation status and tumor location provides a comprehensive picture of cutaneous melanoma in a BRAF-driven, MITF-high model." (PMID 34791221, 2022).
cutaneous melanoma (continued). "In addition to showing a strong correlation with MITF expression in the skin cutaneous melanoma dataset in The Cancer Genome Atlas (TCGA), HVEM expression was recently shown to be strongly correlated with the expression of specific molecules upstream or downstream of MITF." (PMID 38351314, 2024). "Because case 13 grouped near cutaneous melanoma by t-SNE analysis, we evaluated multiple melanocytic markers (HMB-45, Melan-A, MiTF) that were all negative." (PMID 39636306, 2025). "A negative correlation of MITF and PTGS2 is also observed in the TCGA dataset for skin cutaneous melanomas." (PMID 32978520, 2020). "After excluding patients positive for CDKN2A/CDK4 pathogenic variants and those affected by non-cutaneous melanomas, our study cohort comprised 984 cutaneous melanoma patients, 22 MITF+ and 962 MITF−." (PMID 32054529, 2020). "Interestingly, the same negative correlation has been observed on MITF and AXL expression levels interrogating cutaneous melanoma data deposited in cBioPortal database." (PMID 38472212, 2024).
deafness (41 papers, 2009 to 2025). An inherited or acquired condition characterized by the complete loss of the ability to hear from one or both ears. "The analysis reported in this study finds that variants in the vicinity of MITF increase deafness risk relative to wild-type alleles." (PMID 36104420, 2022). "This conclusion is supported by a recent study on deafness in Australian Cattle Dogs, which also identified an association between the MITF locus and deafness." (PMID 36104420, 2022). "More recently, mutations in MITF have been identified in patients with Coloboma who also show osteopetrosis, microphthalmia, macrocephaly, albinism, and deafness." (PMID 35682684, 2022). "Heterozygous mutations in the MITF gene are strongly related to pigmentation disorders and deafness called Waardenburg Syndrome 2A (WS2A)." (PMID 36570450, 2022). "In the pathogenesis of deafness in WS patients, studies have found that the potassium pump function of melanocytes in microphthalmia-associated transcription factor (MITF) mutant mouse models is abnormal and cannot maintain endolymphatic potential." (PMID 33597923, 2020). "MITF gene mutations cause abnormal depigmentation of hair and skin, sometimes associated with total or partial deafness." (PMID 30872653, 2019). "Waardenburg and Tietz syndromes are associated with mutations in MiTF, leading to partially similar phenotypes to FA, like deafness, missing bones, weak skin pigmentation and microphtalmia." (PMID 31219578, 2019). "In humans and mice, loss-of-function mutations in MITF cause severe symptoms including: coloboma, osteopetrosis, microphthalmia, albinism and deafness." (PMID 31703548, 2019). "In humans, heterozygous mutations in MITF are associated with Waardenburg syndrome type 2 and Tietz syndrome, which are characterized by deafness, and which can include premature hair graying and heterochromia iridis." (PMID 30651300, 2019). "Our results showed that mutations in SOX10 and MITF are two major causes for deafness associated with WS2." (PMID 27759048, 2016). "Mutations in MITF were shown to be responsible for deafness in a Franches-Montagnes colt and in German Fleckvieh cattle, Chinese Rongchang pigs, and Hedlund white American mink." (PMID 26664958, 2015). "In humans, mutation of MITF results in Waardenburg Syndrome IIa, a condition characterized by white forelock and deafness." (PMID 19828018, 2009). "MITF can also regulate the proliferation and differentiation of melanocytes and MITF mutations, which are associated with phenotypes of Waardenburg syndrome, such as deafness and hypopigmentation in humans." (PMID 36499416, 2022). "Interestingly, none of the GWAS conducted to date in the Dalmatian breed have positively identified MITF as a risk locus for either bilateral or unilateral deafness." (PMID 36104420, 2022). "In humans, mutations in MITF have been identified in patients with Waardenburg syndrome (WS) type 2A and Tietz syndrome, leading to pigmentation defects such as patches of light skin and iris heterochromia and deafness." (PMID 35682684, 2022). "Our previous work reported a phenotype of miniature pigs with deafness and depigmentation which was caused by a mutation in the region of the melanocyte-specific promoter of microphthalmia-associated transcription factor (MITF) gene." (PMID 30635004, 2019). "The authors concluded that MITF is involved in deafness in Dalmatians and that possible causative mutation or mutations might be in the non-coding sequence of MITF, but no actual gene mutation was identified or suggested to be a candidate." (PMID 26664958, 2015). "While the reduced risk of deafness in Australian Cattle Dogs with bilateral masks may be due to a weak expression of the sw allele of MITF, it is also possible that a gene other than S, possibly a locus linked to a CHSD locus, is also involved." (PMID 23107143, 2012).